FTO (FTO alpha-ketoglutarate dependent dioxygenase)
Diseases named in the same sentence as FTO in open-access papers (continued):
Sharing a sentence is not in itself a finding about the gene and the disease.
Obesity (continued). "For example, a number of single nucleotide polymorphisms (SNPs) in the fat mass and obesity (FTO) gene such as rs9939609, rs9930506, rs6499640, rs8050136 and rs1558902 were reported to be associated with obesity in both children and adults." (PMID 38556726, 2024). "An inverse correlation has been demonstrated between FTO and m6a, which is implicated in adipogenesis and demonstrates how FTO directly modulates obesity at the level of m6A." (PMID 38892547, 2024). "The FTO rs9939609 and rs1421085 are associated to an increased risk of obesity among children and adolescents." (PMID 38973101, 2024). "About half the world's population carries at least one of the obesity‐related risk alleles of different polymorphisms of the FTO gene." (PMID 38556726, 2024). "This study represents the first comprehensive investigation into the potential of bioactive compounds in Little Millet grain extract as inhibitors of the fat mass and obesity-associated (FTO) protein." (PMID 39494311, 2024). "In this study, we investigated the association of the FTO gene variant rs9939609 with obesity-related parameters in T2DM and CVD patients." (PMID 39257882, 2024). "Multiple studies have hinted at the potential influence of particular genes linked to obesity risk (i.e., FTO, MC4R, and TMEM18) on GWG, emphasizing the necessity for in-depth investigations into their roles." (PMID 38613027, 2024). "This study revealed that the AG genotypes of the leptin (LEP) A-2548G polymorphism and the AA genotypes of the fat-mass and obesity-associated protein (FTO) rs9939609 polymorphism were associated with a higher risk of obesity." (PMID 39766314, 2024). "For the FTO gene variant, rs9939609, which is strongly linked to obesity, Korean women with the A allele have an incidence of obesity 1.28 times higher than those with the TT genotype." (PMID 39765884, 2024). "The present study aimed to assess the influence of the rs9930506 FTO gene polymorphism on the success of a comprehensive weight loss intervention in male adolescents with overweight and obesity." (PMID 38556726, 2024). "A study of genetic association indicated that the SNP rs9930506 of the FTO gene has a strong association with obesity indices such as weight and hip circumference." (PMID 38556726, 2024). "Aside from the association of FTO with the progression of many cancers, obesity, and type 2 diabetes mellitus, some investigators link this enzyme with Alzheimer’s disease and nonalcoholic steatohepatitis too." (PMID 39329974, 2024). "Given the known associations between the FTO gene and obesity, it is important to examine the role of variants in this gene in bariatric surgery outcomes." (PMID 38674326, 2024). "Of note, many researchers in the last few years associated rs9939609 in particular and FTO overexpression in general with dietary habit changes that are responsible for the development of obesity." (PMID 39329974, 2024). "Another study, which utilized sequencing of the chromosome 16 fragment encoding the FTO gene, has shown a strong correlation between rs9930506 polymorphism and obesity and being overweight in males and the rs1421085 variant and obesity in females." (PMID 38892547, 2024). "The FTO gene, which is implicated in fat mass and obesity, highlights the genetic contributions to the obesity-diabetes nexus." (PMID 39469345, 2024). "The first discovered demethylase was alpha-ketoglutarate-dependent dioxygenase FTO (also known as fat mass and obesity-associated protein) that was initially described as an m6A demethylase but was later found to demethylate m1A as well." (PMID 39459530, 2024). "The present study reported that both FTO variants were in moderate linkage disequilibrium and were associated with obesity in the Punjabi population." (PMID 39253342, 2024). "The fat mass and obesity-associated protein (FTO), first identified as m6A demethylase, is involved in the deposition of triglycerides in hepatocytes and promotes adipogenesis and obesity." (PMID 39494311, 2024).
Obesity (continued). "An interesting study found a relationship between the methylation level of the FTO gene and its polymorphism in increasing the risk of obesity." (PMID 39200098, 2024). "The presence of the T allele in the two rs9939609 and rs17817449 polymorphisms in the FTO gene was associated with an increased risk for the development of T2D in Iraqi individuals with obesity." (PMID 38674326, 2024). "In this meta‐analysis, we confirmed that a variant in the FTO gene is significantly associated with an increased risk of overweight or obesity in children and adolescents." (PMID 38973101, 2024). "Recently, Gholami, through the identification of common variants associated with BC, obesity, and diabetes, found that the FTO gene is a major gene shared between these three diseases, with rs9930506 as one of those variants involved." (PMID 39040764, 2024). "Dietary protein levels also interacted with some genes, including the FTO gene (rs1558902) (FTO = Fat Mass and Obesity-Associated Gene superfamily of hydroxy alpha-ketoglutarate-dependent hydroxylase)." (PMID 39064800, 2024). "Associations between the fat mass and obesity-associated (FTO) gene and obesity are well-established." (PMID 39080362, 2024). "The lead signals of common obesity-associated variants are located within the first intron of the FTO (fat mass and obesity-associated) gene, being the most significant and impactive single-nucleotide polymorphism (SNP) clusters in obesity inheritance." (PMID 39873006, 2024). "FTO protein, originally known to be associated with increased body mass and obesity in children and adults, is the first identified m6A demethylase to perform m6A demethylation activity on mRNAs." (PMID 38782769, 2024). "The A allele of the rs9939609 variant of the gene FTO is most commonly associated with weight gain and obesity, and also influences a higher risk of type 2 diabetes." (PMID 39458556, 2024). "Although FTO was identified primarily as a candidate gene associated with obesity risk, it has been predicted bioinformatically to be an Fe(II)/αKG-dependent dioxygenase homologous to bacterial DNA dioxygenase AlkB." (PMID 39329974, 2024). "The present investigation indicated that both the FTO 30685T/G (rs17817449) and -23525T/A (rs9939609) polymorphisms have a key impact on an individual’s vulnerability to obesity in this population." (PMID 39253342, 2024). "The impact of genetic variants located within the first intron of the FTO gene on the occurrence and development of MetS, BMI, and obesity was also analyzed in other populations." (PMID 38892547, 2024). "This study further underscores the association between obesity and EC, emphasizing the potential of utilizing FTO as a therapeutic target for EC." (PMID 39660878, 2024). "This study aimed to comprehensively analyze the problem of overweight and obesity among psoriatic patients by investigating the influence of body mass composition, anhedonia and depression, environmental factors and FTO gene polymorphisms." (PMID 38540130, 2024). "FTO polymorphisms rs9939609 was the first identified locus that has been confirmed to be strongly associated with obesity in numerous large-scale trials." (PMID 39483856, 2024). "N6‐methyladenosine (m6A) always plays an important role in tumor progression, and fat mass and obesity‐associated gene (FTO) works as the m6A demethylase." (PMID 39692250, 2024). "Further animal research on mice and pigs provide more evidence in favor of the association studies linking FTO mutations to obesity." (PMID 39203789, 2024). "Recent advances in genomic research have increasingly focused on the fat mass- and obesity-associated (FTO) gene due to its notable correlation with obesity." (PMID 39175477, 2024). "Still, many data confirm the existence of pathogenic gene variants, e.g., Fat Mass and Obesity Associated Gene (FTO), beta-2-adrenergic receptor (ADRB2) gene, melanocortin-4 receptor (MC4R) and others with obesity." (PMID 38397196, 2024).
Obesity (continued). "Our results suggest that among the variables studied, the most associated with risk for class III obesity were the FTO rs9939609 AA risk genotype and physical inactivity." (PMID 38610209, 2024). "We searched PubMed, Google scholar, Web of Science and Scopus until January 2024 to find studies that investigate the association between different SNPs of FTO gene and the risk of overweight/obesity in children and adolescents." (PMID 38973101, 2024). "It involved 112 adults with obesity, each with at least one minor allele in the FTO, LEP, LEPR, or MC4R polymorphism." (PMID 38398881, 2024). "At the same period, two independent teams also reported that the FTO gene was associated with obesity." (PMID 38973101, 2024). "FTO is associated with human obesity and energy homeostasis, demethylating m6A in cellular mRNA and other RNA species." (PMID 38545841, 2024). "The role of FTO genetic polymorphisms in the predisposition to obesity development in Egyptian populations requires further investigations, particularly in relation to the epidemiological transition and to calorie-rich food." (PMID 39706986, 2024). "Variants of the fat mass and obesity-associated (FTO) gene, including rs9939609, rs1121980, and rs1421085, have been linked to an increased risk of obesity." (PMID 39203810, 2024). "Recently, interest in the FTO gene has been renewed following a systematic analysis exploring the potential overlap of known GWAS risk variants for obesity, T2DM and breast cancer." (PMID 39251829, 2024). "Several studies have confirmed the association of rs1421085 FTO with the risk of developing obesity." (PMID 38674326, 2024). "The SNP with the strongest association with BMI, WBFFM and WBFM, rs17817288[G], is an intron variant mapped to the fat mass and obesity-associated (FTO) gene." (PMID 38538606, 2024). "The m6A erasers, accounting for the demethylation of m6A in RNAs, include fat mass and obesity-associated (FTO) andα-ketoglutarate-dependent dioxygenase AlkB homolog 5 (ALKBH5)." (PMID 38545555, 2024). "Individuals carrying the FTO rs178117449 risk allele have been found to have an increased risk of obesity." (PMID 39706986, 2024). "Among 46 identified point mutations within FTO gene, mutation SNP rs9939609 has the strongest effect on an increase in body weight and occurrence of overweight and obesity (including their consequences, namely type 2 diabetes)." (PMID 39671348, 2024). "For the FTO SNP (rs9939609; T>A), the risk allele (A) frequency was similar between the normal-weight group (0.32) and the obesity group (0.27)." (PMID 39408369, 2024). "According to our meta‐analysis and systematic study, we have found that the FTO rs9939609 and rs1421085 are associated with an increased risk of obesity among children and adolescents." (PMID 38973101, 2024). "A recent study reported that the obesity‐related A allele of rs9939609 polymorphism of the FTO gene was associated with changes in appetite and food cravings during an intervention with hypocaloric diets." (PMID 38556726, 2024). "The first obesity susceptibility locus discovered by GWAS mapped to 16q12.2, proximal to the fat mass and obesity-associated (FTO) gene which has been recognised as a regulator in DNA repair mechanisms, DNA damage and inflammatory responses." (PMID 39251829, 2024). "The obesity and diabetes genes fat mass and obesity-associated (FTO), carnitine palmitoyl transferase 1A (CPT1A), leptin receptor (LEPR), and lamin A/C (LAMIN) genes were significantly down-regulated in the cardamom group." (PMID 38558676, 2024). "The common FTO polymorphism with a T-to-A change (rs9939609) is strongly associated with an increased risk of obesity development in various populations." (PMID 39336728, 2024). "Since the FTO gene is a genetic factor of obesity, researchers have focused on a potential association between dyslipidemia and the FTO gene." (PMID 39483856, 2024).
Obesity (continued). "Currently, the FTO gene, located on chromosome 16, is regarded as a key player in the genetics of obesity, with significant impact revealed in genome-wide association studies." (PMID 38540130, 2024). "FTO has been intensely studied in humans because it is the QTL most strongly associated with obesity." (PMID 39669404, 2024). "The FTO gene encodes α-ketoglutarate-dependent dioxygenase, with many variants associated with obesity-related traits." (PMID 39766774, 2024). "Spontaneous abortion (SA) is reported to be associated with Fat Mass And Obesity-Associated FTO genotype and dietary intake of selenium." (PMID 39758312, 2024). "Some of them—like PPARγ mutation (rs1801282; C>G; Pro12Ala)—were described in elderly subjects to be a risk factor for increased obesity, especially in subjects with high carbohydrate intake with the co-presence of one rs9939609 allele of FTO gene." (PMID 38397196, 2024). "We designed this case-control study to evaluate the association of two FTO variants 30685T/G (rs17817449) and -23525T/A (rs9939609) with obesity risk in the population of Punjab." (PMID 39253342, 2024). "The most studied variant from FTO is the SNP rs9939609 (g.87653T>A), in which carriers of the risk allele A (homozygous or heterozygous) have increased odds for obesity and higher calorie, fat, and carbohydrate intake." (PMID 39130748, 2024). "The progression from obesity to diabetes is linked to FTO’s dual influence on energy balance and adipose tissue, where its regulatory effects can contribute to systemic metabolic dysfunctions, such as insulin resistance, that characterize diabetes." (PMID 39744011, 2024). "This is critical because our study revealed that many other polymorphisms showed a stronger association with obesity and overweight than FTO rs9939609 in the same studies." (PMID 38973101, 2024). "The variations in the single‐nucleotide polymorphisms (SNPs) of the fat mass and obesity (FTO)‐associated gene have been linked to being overweight or obese in children." (PMID 38973101, 2024). "Due to these controversies, additional studies are needed to confirm the risk allele of the FTO rs17817449 SNP associated with obesity." (PMID 39706986, 2024). "For example, hypomorphisms in the cilia gene Rpgrip1l, found within the fat mass and obesity-associated FTO locus, have been shown to cause obesity." (PMID 38353726, 2024). "Among the genes associated with obesity, the FTO (fat mass and obesity-associated) gene was the first robust locus identified through genome-wide association studies (GWASs) to show a significant association with body mass index (BMI) and body fat percentage." (PMID 39858551, 2024). "The rs7132908 (FAIM2) was found to be significantly associated with obesity, and FTO was the first GWAS-identified obesity gene." (PMID 38997780, 2024). "The current study revealed that FTO rs17817449 TT genotypes were significantly associated with the risk of overweight and obesity in DS children." (PMID 39706986, 2024). "The fat mass and obesity-associated gene (FTO) is one of the early identified genes linked to obesity in various populations." (PMID 39706986, 2024). "Polymorphisms in the FTO (fat mass and obesity-associated) gene, for instance, are associated with increased body mass index (BMI) and obesity." (PMID 39731011, 2024). "The FTO gene variation is associated with obesity and influences appetite regulation and energy balance, increasing the risk of T2DM." (PMID 39514584, 2024). "In this study, we have found that the FTO rs9939609 and rs1421085 are associated to an increased risk of obesity among children and adolescents." (PMID 38973101, 2024). "Previously published analyses based on much larger studies and meta-analyses conducted on a broader population indicate that FTO genetic variants correlate with obesity." (PMID 38892547, 2024).
Obesity (continued). "The present results suggested that FTO 30685T/G (rs17817449) and -23525T/A (rs9939609) are the risk factors for obesity with regulation of body mass and composition." (PMID 39253342, 2024). "Recent studies have demonstrated that ALKBH1, ALKBH5, ALKBH8, and FTO function as tRNA demethylases, which are associated with a range of diseases, including obesity, osteoporosis, diabetes and multiple cancers." (PMID 38902235, 2024). "Single nucleotide polymorphisms in the FTO gene are shown to be associated with obesity and various cancers such as breast, prostate and lung cancer." (PMID 39600630, 2024). "This is one of the first studies conducted on Egyptian DS children, which revealed that the FTO rs17817449 T allele and GT, TT, (GT + TT) genotypes were associated with increased risk of overweight and obesity." (PMID 39706986, 2024). "Fat mass and obesity-associated protein (FTO) is a pivotal regulator of adipogenesis and is a determinant of obesity development." (PMID 38363215, 2024). "Genome-wide association analysis (GWAS) revealed the first genetic factor closely related to human obesity: Fat mass and obesity-associated (FTO) gene." (PMID 39483856, 2024). "The intricate interplay between genetic variants of FTO, environmental factors, and metabolic pathways underscores the significance of this demethylase in the pathogenesis of obesity." (PMID 39744011, 2024). "Recent studies have broadened our understanding of the FTO gene, showing that rs9939609 and rs17817449 have strong linkage imbalances and that haplotype enhances susceptibility to obesity." (PMID 39483856, 2024). "When the AA genotype is accompanied by enhanced methylation of the FTO gene, the risk of obesity is particularly increased." (PMID 39200098, 2024). "Collectively, all this information suggests that the FTO rs9939609 polymorphism was associated with several phenotypes associated with obesity and insulin resistance, particularly under the AA vs. T allele/recessive model." (PMID 39858551, 2024). "FTO, the first identified m6A methyltransferase, plays a crucial role in controlling fatty acid transport, synthesis, metabolism, and susceptibility to obesity in eukaryotic cells." (PMID 38365891, 2024). "Longitudinal studies are needed to elucidate the temporal dynamics of how the FTO rs9939609 polymorphism and related genetic factors influence fat oxidation and obesity-related phenotypes over time." (PMID 39858551, 2024). "Our study, a placebo-controlled randomized trial, delves into the efficacy of specific dietary fiber supplements—glucomannan, inulin, and psyllium—in individuals with obesity-related genetic polymorphisms within genes such as FTO, LEP, LEPR, and MC4R." (PMID 38398881, 2024). "This discovery has been consistently replicated, highlighting the FTO gene’s critical role in obesity predisposition and related metabolic traits." (PMID 39858551, 2024). "A previous genome-wide search for genes susceptible to type 2 diabetes revealed that the obesity-related FTO gene (an alpha-ketoglutarate-dependent dioxygenase gene) is highly correlated with an increased BMI and overweight status." (PMID 39194753, 2024). "Research into the relationship between FTO and cancer risk began shortly after SNPs in the human FTO gene were linked to obesity." (PMID 39744011, 2024). "The study aims to assess the connection between SNPs in the FTO gene and obesity susceptibility in this population due to the high prevalence of overweight and obesity in the region." (PMID 39253342, 2024). "This demonstrates that possessing two copies of the FTO A allele (i.e., AA genotype) is associated with a higher predisposition to the development of obesity-related phenotypes." (PMID 39858551, 2024). "Although many genes are known to influence polygenic obesity, polymorphisms of fat mass and the obesity-associated protein (FTO) gene were quickly recognized as highly influential regarding BMI and body adiposity." (PMID 38892547, 2024).